NLRP3 (NLR family pyrin domain containing 3)
Diseases named in the same sentence as NLRP3 in open-access papers (continued):
Sharing a sentence is not in itself a finding about the gene and the disease.
atherosclerosis (continued). "Due to the importance of NLRP3 in atherosclerosis, different ways have been proposed for its inactivation." (PMID 33664731, 2020). "Reactive oxygen species (ROS) play an essential role in NLRP3 inflammasome activation in atherosclerosis." (PMID 31993073, 2020). "Recent studies have shown that the activation of the NLRP3 inflammasome is involved in the progression of various inflammatory diseases, such as type 2 diabetes, atherosclerosis, and Muckle-Wells syndrome." (PMID 33041826, 2020). "Sustained activation of NLRP3 by exogenous or endogenous triggers thus aggravates chronic inflammatory diseases such as atherosclerosis or worsen acute inflammatory conditions such as fulminant hepatitis or myocardial infarction." (PMID 32849554, 2020). "After lethally irradiated bone marrow was reconstituted with wild-type, NLRP3-, ASC-, or IL1α/β-deficient bone marrow, mice had lower levels of IL-18 and IL-1 family cytokines and showed decreased atherosclerosis." (PMID 32596261, 2020). "Our discussion highlights the literature supporting HIV-1 infection as a stimulator of the NLRP3 inflammasome as a driver of atherosclerosis." (PMID 32596261, 2020). "Because inflammatory response and NLRP3 inflammasome play an important role in the development of atherosclerosis, the NLRP3 inflammasome as the therapeutic target has become a hot topic in the research of atherosclerotic drugs." (PMID 32328119, 2020). "H2S showed inhibiting NLRP3 role in retinal pigment epithelial cell inflammation, colitis, and atherosclerosis." (PMID 32116706, 2020). "In an in vitro study using PMA-induced macrophages, scientists have demonstrated the inhibitory effect of curcumin against NLRP3 inflammasome, suggesting that curcumin ameliorates the development and progression of atherosclerosis." (PMID 32650482, 2020). "In this review, we focused on the features of NLRP3 inflammasomes and their significance for atherosclerosis, especially concerning mitochondria." (PMID 32664349, 2020). "Specifically, dysregulated NLRP3 inflammasome—an innate immune sensor for tissue damage—is responsible for initiation of sterile inflammation in the artery that leads to atherosclerosis." (PMID 33290264, 2020). "Many studies have shown that the NLRP3 inflammasome is involved in diseases such as type 2 diabetes, atherosclerosis, colitis, Parkinson’s disease, and multiple sclerosis, as well as psychological disorders." (PMID 33041826, 2020). "Increasing studies have reported that BBR exhibits an inhibitory effect on NLRP3 inflammasome and is a potential candidate for the treatment of various diseases such as atherosclerosis, gouty arthritis, and liver injury." (PMID 32194416, 2020). "The role of the NLRP3 inflammasome in atherosclerosis was demonstrated using low-density lipoprotein (LDL) receptor deficient mice, a model for familial hypercholesterolemia." (PMID 32596261, 2020). "The researches indicated that the abnormal activation of NLRP3 inflammasome was related to the pathogenesis of various autoimmune, chronic inflammatory and metabolic diseases, including gout, atherosclerosis and type 2 diabetes 2-4." (PMID 33110394, 2020). "A few studies have demonstrated the important function of the NLRP3 inflammasome for the pathogenesis of atherosclerosis." (PMID 32664349, 2020). "On the contrary, NLRP3 inflammasome activation accelerates atherosclerosis induced by HMGB1 secretion, indicating that HMGB1 is a key downstream signaling molecule of NLRP3 inflammasome activation." (PMID 32161574, 2020). "Metformin also inhibited the activation of the NLRP3 inflammasome in ApoE−/− mice and inhibited atherosclerosis in diabetes." (PMID 32328119, 2020). "CD36 is involved in macrophage foam cell formation and atherosclerosis progression by mediating endocytosis and conversion of oxLDL into cholesterol crystals, thus promoting complement and NLRP3 inflammasome activation." (PMID 33117348, 2020).
atherosclerosis (continued). "Persistent and abnormal NLRP3 signaling is the basis of many chronic and degenerative diseases, including Stargardt disease type 1, Alzheimer's disease, atherosclerosis, atrial fibrillation, osteoarthritis, and cancer." (PMID 32148650, 2020). "It has been reported that the inflammasome Nlrp3-caspase-1-IL-1β pathway triggers vascular endothelial inflammation in the progression of atherosclerosis." (PMID 31993073, 2020). "To date, only few studies correlated NLRP3 and MyD88 with hyperglycemia damages, like diabetes-induced endothelial inflammation and atherosclerosis." (PMID 33096896, 2020). "Since this first report, there has been vast interest in determining the relationship between NLRP3 activation and other inflammatory conditions including type 2 diabetes, atherosclerosis, and steatohepatitis, among others." (PMID 32252777, 2020). "Remarkably, a recent study found that tranilast exhibited antivascular inflammation and anti-atherosclerosis properties via increasing NLRP3 ubiquitination and impeding NLRP3 inflammasome activation." (PMID 32948742, 2020). "Inhibiting NLRP3, an activator of IL-1β, causes a reduction in the expression and release of inflammatory molecules such as VCAM-1 and ICAM-1 producing atherosclerosis resistance." (PMID 32733941, 2020). "NLRP3 inflammasome activation in these cells and cardiomyocytes initiates immune inflammatory reactions and plays fundamental roles in atherosclerosis, ischemia/reperfusion (I/R) injury, and heart failure (HF) with different etiologies." (PMID 32508013, 2020). "Hyperuricemia can promote the development of atherosclerosis by regulating inflammatory signal pathways, such as NLRP3-inflammasomes, macrophage M1/M2 polarization, and hs-CRP, and ULT can significantly reverse the formation of atherosclerotic plaques." (PMID 33304270, 2020). "Activation of the NLR family, pyrin domain-containing 3 (NLRP3) inflammasome and subsequent interleukin (IL)-1β release induces atherosclerosis and heart failure." (PMID 32358544, 2020). "Many studies have demonstrated that atherosclerosis is accelerated via activation of the NLRP3 inflammasome." (PMID 31993073, 2020). "The cytokine IL-1β, which is downstream of the NLRP3 inflammasome, acts as an important mediator for the development of atherosclerosis and was quantified by ELISA." (PMID 31993073, 2020). "Many clinical and experimental studies have reported that the NLRP3 inflammasome contributes to endothelial dysfunction in atherosclerosis." (PMID 31993073, 2020). "Mechanistically, the oxLDL and ChC were identified to be the pivotal activators of NLRP3 inflammasome in the context of atherosclerosis." (PMID 33290264, 2020). "NOD-like receptor family pyrin domain containing 3 (NLRP3) inflammasome activation contributes to the progression of atherosclerosis, and autophagy inhibits inflammasome activation by targeting macrophages." (PMID 33505579, 2020). "The NLRP3 inflammasome induces vascular inflammation, leading to the progression of atherosclerosis." (PMID 32273846, 2020). "To further clarify the exact relationship between the NLRP3 inflammasome and atherosclerosis, and the specific mechanism, we need to provide more reliable experimental evidence." (PMID 32328119, 2020). "NLRP3 inflammasome activation was proven to participate in numerous processes related to atherosclerosis and cardiovascular disease." (PMID 32664349, 2020). "Among the metabolic danger signals, cholesterol crystals are now regarded as the main trigger for NLRP3 activation in atherosclerosis." (PMID 32751658, 2020).
atherosclerosis (continued). "Arglabin, a plant-derived compound, inhibited the activity of the NLRP3 inflammasome and significantly reduced the production of IL-1α, IL-1β, and IL-18, reducing the production of proinflammatory mediators to alleviate atherosclerosis." (PMID 32328119, 2020). "Most studies have proved that targeting at the initiation and activation of the NLRP3 inflammasome can effectively delay the process of atherosclerosis, and thus reduce the hospitalization rate of patients." (PMID 32328119, 2020). "Atherosclerosis is another condition in which the activity of the NLRP3 inflammasome promotes pathogenesis." (PMID 32751530, 2020). "Using drugs targeting at the NLRP3 inflammasome to treat atherosclerosis is promising, but it also needs further pharmacological studies to verify the efficacy and further experimental epidemiological studies to ensure the safety." (PMID 32328119, 2020). "Excessive activation of the NLRP3 inflammasome contributes to the pathogenesis of a wide variety of diseases, such as diabetes, atherosclerosis, and obesity-induced insulin resistance." (PMID 32161574, 2020). "It was shown that ox-HDL, ox-LDL, and HDL regulate activation of the NLRP3 inflammasome and downstream cytokines, and thus take part in the pathogenesis of atherosclerosis." (PMID 32664349, 2020). "Tan IIA significantly attenuated both the priming and activation steps during NLRP3 inflammasome assembly, and thereby decreases oxLDL-induced sterile inflammation and ultimately prevents the development of atherosclerosis." (PMID 33290264, 2020). "The NLRP3 (NACHT, LRR and PYD domains-containing protein 3) inflammasome has been implicated in a variety of diseases, including atherosclerosis, neurodegenerative diseases, and infectious diseases." (PMID 32646056, 2020). "NLRP3 inflammasome has been shown as the primary generator responsible for IL-1 production in atherosclerosis and other CVDs." (PMID 32226786, 2020). "During the development of atherosclerosis, the NLRP3 inflammasome is inappropriately activated by cholesterol crystals, oxidized low-density lipoprotein (oxLDL), and abnormal hemodynamics, which results in massive inflammation." (PMID 33505579, 2020). "Among other things, it reduces the activation of NLRP3 inflammasome and NF-κB and thus inflammatory reactions that are important in the development of atherosclerosis." (PMID 30927246, 2020). "We review the evidence defining the role of HIV-1 infection in activation of the NLRP3 inflammasome and the role of NLRP3 activation in the development of atherosclerosis." (PMID 32596261, 2020). "No reports have addressed fucoidan-mediated regulation of the NLRP3 inflammasome and autophagy in atherosclerosis." (PMID 33505579, 2020). "As the core of inflammatory response, NLRP3 inflammasome plays a key role in many diseases, including familial periodic inflammation, type 2 diabetes mellitus, Alzheimer’s disease, and atherosclerosis." (PMID 32059742, 2020). "The data suggest that fucoidan can inhibit NLRP3 inflammasome activation by enhancing p62/SQSTM1-dependent selective autophagy to alleviate atherosclerosis." (PMID 33505579, 2020). "One such mechanism is NLRP3 inflammasome activation by cholesterol crystals, which are present in lesions of atherosclerosis." (PMID 32118048, 2020). "To explore the effect of fucoidan on NLRP3 inflammasome and IL-1β production in atherosclerosis, we examined the serum secretion of IL-1β using ELISA." (PMID 33505579, 2020). "The present study is the first description that fucoidan, one of the most abundant extracts obtained from brown seaweed, can reverse the activation of the NLRP3 inflammasome that accelerates the development of atherosclerosis." (PMID 33505579, 2020). "The ox-LDLs, cholesterol crystals, and other substances induced the activation of the NLRP3 inflammasome and thus promoted the generation of atherosclerosis." (PMID 32328119, 2020).
atherosclerosis (continued). "Increased activation of NLRP3 has been related to several chronic pathologies, including neurodegenerative diseases, atherosclerosis, type-II diabetes, fibrosis, and rheumatoid arthritis." (PMID 31600880, 2019). "The NLRP3 inflammasome and the IL (interleukin) family cytokines are central mediators of vascular inflammation during the process of atherosclerosis." (PMID 31191743, 2019). "Numerous studies have shown that the activated NLRP3 inflammasome was involved in the pathogenesis of metabolic diseases, such as type 2 diabetes mellitus, atherosclerosis, and obesity." (PMID 31097920, 2019). "Our results will help improve our understanding of the relationships among LPC, LD biogenesis, and NLRP3 inflammasome activation in the pathogenesis of atherosclerosis." (PMID 31998284, 2019). "NLRP3 (NOD-like receptor family, pyrin domain-containing protein 3) activation has been linked to several chronic pathologies, including atherosclerosis, type-II diabetes, fibrosis, rheumatoid arthritis, and Alzheimer’s disease." (PMID 31600880, 2019). "The cyclic reaction mechanism that activates NLRP3 also aggravates atherosclerosis, leading to stroke." (PMID 31174550, 2019). "The NLRP3 inflammasome, a multiprotein cytosolic complex that activates the IL-1 family of cytokines, plays an important role in atherosclerosis (AS)." (PMID 30761006, 2019). "Cholesterol crystals induce Nrf2-related signaling pathways, including the caspase-1-independent IL-1 signaling and NLRP3/caspase-1-dependent IL-1 pathways, leading to atherosclerosis." (PMID 31354731, 2019). "Our study identifies NFAT5 as a new and essential transcription factor that is required for the early activation of NLRP3-inflammasome-mediated endothelium innate immunity, contributing to the formation of atherosclerosis under hypertonic stress induction." (PMID 31429763, 2019). "Chronic inflammatory responses by the NLRP3 inflammasome are involved in the course of various diseases such as gout, atherosclerosis, Alzheimer’s disease, T2DM, and stroke." (PMID 31174550, 2019). "The crucial role of the inflammasome including ASC and NLRP3 in atherosclerosis is the most studied." (PMID 31871426, 2019). "Oral supplementation with cis-PAO inhibits both hyperlipidemia-induced UPR signaling and NLRP3 inflammasome activation in macrophages in plaques, resulting in reduced atherosclerosis in mice." (PMID 31422082, 2019). "Currently, strong evidence for the role of NLRP3 activation has been demonstrated in pathogenesis atherosclerosis." (PMID 31118894, 2019). "Here we postulated that high-salt-induced NFAT5 controls the inflammasome activation by directly regulating NLRP3, which mediates the expression of inflammatory- and adhesion-related genes in vascular endothelium, resulting in the formation of atherosclerosis." (PMID 31429763, 2019). "The NLRP3 inflammasome is clearly involved in the pathogenesis of diabetes, atherosclerosis, and infectious disease due to the secretion of IL-1β and IL-18 from this complex." (PMID 30616678, 2019). "NLRP3 participates in the inflammatory component of several diseases such as multiple sclerosis, gouty arthritis, atherosclerosis, Alzheimer’s and Parkinson’s diseases, type 2 diabetes, or cancer." (PMID 31547225, 2019). "Increasing evidence has shown that the activation of NLRP3 inflammasome cascade plays a crucial role in sustained inflammation in different inflammatory diseases, including atherosclerosis, chronic obstructive pulmonary disease, and diabetes." (PMID 31146750, 2019). "Of note, recent experimental results on the involvement of the NLRP3 pathway (a main trigger of IL1-beta release) seems to confirm the pivotal role of specific signaling pro-inflammatory routes in atherosclerosis pathophysiology." (PMID 31312638, 2019). "Recent studies have shown that the NLRP3 inflammasome and IL-1β/IL-18 play important roles in gout, rheumatoid arthritis, atherosclerosis, DM, and oxalate-related nephropathy diseases." (PMID 29929501, 2018).
atherosclerosis (continued). "The NLRP3 inflammasome is closely related to various diseases, such as chronic inflammation, senility, autoinflammatory syndrome, metabolic diseases, and atherosclerosis and leads to excessive release of inflammatory factors." (PMID 30622955, 2018). "Activation of NLRP3 inflammasomes increased lipid deposition and promoted atherosclerosis progression." (PMID 29773990, 2018). "The data presented in the current study demonstrated that nicotine-induced NLRP3 inflammasome activation, inflammatory response, and subsequent pyroptosis in the setting of atherosclerosis." (PMID 29416034, 2018). "Several recent reviews have also focussed on NLRP3 as nexus between oxidized lipids and inflammatory cytokine release in atherosclerosis." (PMID 29997514, 2018). "Inflammatory signals involved in atherosclerosis, including cholesterol crystals, hypoxia, and turbulent flow, activate the NLRP3 inflammasome, which is a multi-protein assembly that integrates these signals and specifically activates the IL-1β isoform." (PMID 29922680, 2018). "The activation of lysosome biogenesis by TFEB overexpression suppresses cholesterol crystal-induced NLRP3 inflammasome, attenuating the progression of atherosclerosis, in vitro and in vivo." (PMID 29997514, 2018). "Ogg1 deficiency in atherosclerotic mice induces larger plaque and greater amount of lipid content, while both knockout of Ogg1 and NLRP3 rescue the enhanced atherosclerosis observed in Ogg1−/− mice." (PMID 30405440, 2018). "Regarding the association with CVD, type I IFNs present in SLE are considered to have a detrimental impact on the vasculature that promotes atherosclerosis, and this is done by upregulation of NLRP3, caspase-1, and IL-18 in endothelial progenitor cells." (PMID 29954107, 2018). "Nucleotide-binding domain-like receptor protein 3 (NLRP3) plays a crucial role in the pathogenesis of atherosclerosis." (PMID 29850543, 2018). "Increasing evidence has shown that the NLRP3 inflammasome is a potential drug target for ameliorating atherosclerosis." (PMID 30186288, 2018). "Excessive activation of NLRP3 inflammasome has been proven to play a key role in a variety of inflammatory diseases, such as diabetes, Alzheimer's disease, and atherosclerosis." (PMID 29507526, 2018). "Silencing NLRP3 in such models also reduced macrophage infiltration and HHcy-induced atherosclerosis lesions." (PMID 29850631, 2018). "With regard to the regulation of NLRP3 activation in atherosclerosis, this issue can be discussed in two respects: the priming step and the activation step." (PMID 29850631, 2018). "There is a role for both cholesterol and IL1β in this process, because cholesterol crystals activate NLRP3, leading to IL1β production, and activated macrophages are present as foam cells in atherosclerosis." (PMID 29463677, 2018). "The use of cholesterol crystals was central to defining the role of NLRP3 in atherosclerosis and dietary cholesterol has also been shown to induce intestinal inflammation in vivo in zebrafish." (PMID 29997514, 2018). "Recently, there is much interest in the possible role of NOD-like receptor family pyrin domain containing 3 (NLRP3) inflammasome in atherosclerosis." (PMID 29954107, 2018). "Atherosclerosis is a chronic disease resulting in progressive narrowing of arterial vessels due to an imbalance in lipid metabolism, and it was reported that the NLRP3 inflammasome is involved." (PMID 30514828, 2018). "The implication of NLRP3 in atherogenesis is further supported by the fact that the inhibition of NLRP3 reduced plaque formation and decelerate atherosclerosis in mice." (PMID 29954107, 2018). "In conclusion, dietary PUFAs reduce atherosclerosis, in part, by activation of macrophage autophagy and attenuation of NLRP3 inflammasome activation." (PMID 28729463, 2017). "In the progression of atherosclerosis, cholesterol crystals or calcium phosphate crystals are involved in NLRP3 inflammasome-mediated inflammatory responses." (PMID 29259717, 2017).